EGFR (epidermal growth factor receptor)
Diseases named in the same sentence as EGFR in open-access papers (continued):
Sharing a sentence is not in itself a finding about the gene and the disease.
colorectal tumors (continued). "Colorectal tumors with wild-type KRAS are often sensitive to EGFR blockade." (PMID 24304820, 2013). "Given that EGFR, a transmembrane receptor tyrosine kinase, is overexpressed in 25%–75% of colorectal tumors, a significant proportion of patients that may benefit from anti-EGFR agents may also have KRAS mutation." (PMID 23202889, 2012). "We could speculate that in colorectal tumours with pAKT and pMAPK expression a therapeutic strategy targeting these molecular factors may be more appropriate than anti-EGFR therapies." (PMID 22490361, 2012). "However, several reports showed that mutations in genes involved in the Ras-Raf-MAPK pathway, like KRAS and BRAF, are important biomarkers for colorectal tumor patient response to anti-EGFR mAbs." (PMID 23207070, 2012). "The molecular mechanisms underlying response or resistance of epidermal growth factor receptor (EGFR) overexpressing colorectal tumours to anti-EGFR compounds are still largely unknown." (PMID 21559018, 2011). "This technique for determination of EGFR GCN has been validated in colorectal tumors as well." (PMID 19712476, 2009). "Given the correlation between KRAS mutational status and response to both EGFR-mAB and EGFR-TKI in lung and colorectal tumors, we hypothesized that our previously published GEPR is capable of predicting response to cetuximab in metastatic CRC." (PMID 19439077, 2009). "However, patients with colorectal tumors harboring KRAS mutations do not benefit from anti-EGFR treatment." (PMID 39123483, 2024). "Clearly, the LIM1899 cell line is dependent on the EGFR signalling pathway for proliferation in vitro; this result is rather unexpected given that these cells harbour a KRAS mutation, which, in the majority of colorectal tumours, circumvents the EGF signalling pathway inhibition in the clinic." (PMID 35301819, 2022). "Our results highlight that the only evaluation of KRAS mutation status in primary colorectal tumor may be not always adequate to predict response to anti-EGFR therapy of the corresponding CRLM." (PMID 33946899, 2021). "Siravegna and colleagues exploited the circulating tumor DNA to genotype colorectal tumors and tracked clonal evolution during treatment with EGFR-specific antibodies, discovering that the percentage of mutated KRAS clones declines in blood when EGFR-specific antibodies are withdrawn." (PMID 31247937, 2019). "Similarly, we provide evidence in clinical practice that low-frequency subclones of heterogeneous, yet already anti-EGFR resistant clones exist in primitive colorectal tumors, with strong implications for targeted treatment planning and design of future clinical trials." (PMID 31036005, 2019). "Thus, STAT3 determined cell survival in EGFR-positive colorectal tumors." (PMID 30068339, 2018). "Therefore, we decided to analyze whether expression of FOXM1 and/or b-catenin in human colorectal tumors may constitute a predictive factor of response to anti-EGFR therapy." (PMID 28423516, 2017). "Specifically, we hypothesized that RAS pathway mutations (but not EGFR ECD variants) might emerge in colorectal tumours in response to ‘environmental' stress." (PMID 27929064, 2016). "EGFR and KRAS: Approximately 30% to 50% of colorectal tumours are known to have a mutated (abnormal) KRAS, indicating that up to 50% of patients with CRC might respond to anti-EGFR antibody therapy, they only have a reasonable opportunity to derive clinical benefit from the therapy." (PMID 25361007, 2014). "However, if on the one hand we are now able to exclude from anti-EGFR treatment patients with putative refractory colorectal tumours (i.e., those harbouring a K-RAS mutant status), on the other hand we are still incapable to accurately select responding patients among those without K-RAS mutations." (PMID 21559018, 2011). "In addition, among colorectal tumours carrying wild-type KRAS, other additional mutations in genes participating in EGFR signalling may cause resistance to anti-EGFR therapies." (PMID 20670437, 2010).
colorectal tumors (continued). "Taken together, we believe that our observations could bring further insights into the biology of EGFR-expressing colorectal tumours and along with growing clinical data could help clinicians in the future to select better the appropriate anti-EGFR treatment option for the appropriate patient." (PMID 17579627, 2007). "Afatinib markedly inhibited the growth of EGFR-overexpressing DiFi cells (IC50 = 45 nM) and showed activity across other colorectal tumour lines, with IC50 values ranging from 0.33 μM in CCL-221 cells to 1.62 μM in HCT-116 cells." (PMID 40940907, 2025). "The molecular basis of this protective effect involves the regulation of epidermal growth factor receptor (EGFR) overexpression, an early event in colorectal tumor genesis." (PMID 40310348, 2025). "Overall, our study demonstrates that SRC signaling is at the nexus of a cell-autonomous inflammatory program with pro-tumorigenic activities, which explains why BRAFV600E colorectal tumors develop resistance to BRAF/MEK and EGFR inhibitors." (PMID 36759733, 2023). "However, it has been showed that resistance to anti-EGFR therapy may also occur among patients without KRAS mutation in colorectal tumors (KRAS wild-type)." (PMID 33946899, 2021). "Patients with a colorectal tumor bearing WT KRAS, which often expresses WT EGFR, do benefit from cetuximab therapy." (PMID 29685162, 2018). "While a subset of colorectal tumors, apparently wild-type for KRAS, are sensitive to EGFR inhibition, they almost always develop secondary resistance after an initial response." (PMID 30127519, 2018). "The colorectal tumour cell line, HCT8 which over-expresses EGFR, was also treated with LY294002 and AZD8055 and IC50 values determined (12 ± 1.9 uM and 83 ± 2.82 nM respectively)." (PMID 27811956, 2016). "Sera from 72 colorectal tumor patients (67 malignant and 5 benign tumors) were compared with 73 healthy donor sera for the presence of antibodies to CEA, EGFR, ErbB2 and ribosomal P proteins by western blotting or ELISA." (PMID 25889931, 2015). "However, mutations in the K-Ras, B-Raf or PIK3CA genes, common in colorectal tumours, result in structural changes in the corresponding proteins, altered effector binding and permanent activation of downstream signalling pathways, independent of EGFR blockade." (PMID 21712828, 2011). "Using genetically engineered mouse models, patient-derived organoids and xenografts, as well as clinical specimens, we discover that colorectal tumors surviving combined KRAS and EGFR inhibition acquire a Paneth-like cell state-a secretory lineage typically confined to the intestinal crypt." (PMID 41237766, 2025). "In esophageal and colorectal tumors, the antitumor effect of MEDI3622 was superior to that of the EGFR/HER pathway inhibitor, suggesting that MEDI3622 inhibits tumor growth by partially modulating non-EGFR-mediated pathways." (PMID 36466812, 2022). "In colorectal tumors, the G12 KRAS mutation detected in 2 out of 15 samples, is predictive for a lack of response to the EGFR inhibitors cetuximab and panitumumab, associated to primary resistance (RI)." (PMID 33947144, 2021). "To conclude, consumption of a glucose-free, high protein diet (GFHPD), comparable to EGFR-directed antibody-based therapy, efficaciously dampens colorectal tumor burden but does not have additive effects in combination with anti-EGFR therapy." (PMID 34830971, 2021). "It was demonstrated that the combination of PDGFR and EGFR inhibitors (imatinib versus cetuximab) in colorectal tumor graft with mutant PDGFRA R981H (exon 22), identified as a mechanism of primary resistance to EGFR blockade, has a strong anti-tumor activity but with a short-lived effect." (PMID 33213472, 2020). "To end the debate, we set out to investigate the functional relationship between all RASGAPs and tumor growth in the presence and absence of EGFR signaling in colorectal tumors." (PMID 30858928, 2019).
colorectal tumors (continued). "In this study, EGFR hypermethylation was observed in none of the 17 colorectal tumours tested and in 7 of the 17 (24%) normal colon tissue." (PMID 21559018, 2011). "Alternative explanations for the efficacy of cetuximab and panitumumab in colorectal tumors regardless of EGFR overexpression status focus on the ligands to EGFR and potential dysregulation of the amount of ligands produced and released into the extracellular space." (PMID 31616627, 2019). "Our results also highlight the importance of the EGFR-Ras-FOXM1-β-catenin signaling axis in CRC and indicate that the expression of the transcription factor FOXM1 in colorectal tumors may be a potential predictive marker of response to cetuximab therapy in this disease." (PMID 28423516, 2017). "Furthermore, EGFR is expressed in 80% of CRC, and several recent and concordant clinical studies have shown that EGFR status is independent of K-ras mutations in colorectal tumors." (PMID 23865079, 2013). "However, in a larger analysis including 63 colorectal tumours we previously demonstrated that EGFR promoter methylation should not be considered a rare event in colorectal tumours as this biological phenomenon occurred in as many as 39% of all cases analysed." (PMID 21559018, 2011). "In our analysis, EGFR promoter methylation was evident in 30 patients (58%), thus indicating that this biological phenomenon should not be considered an infrequent event in colorectal tumours and confirming our previous report." (PMID 21559018, 2011). "The current standard of not testing colorectal tumours for EGFR expression may not apply for other epithelial tumour histologies." (PMID 19401697, 2009). "Similar to our previous findings of a substantial lack of correlation for EGFR status between primary colorectal tumours and corresponding metastases, we also noticed a substantial variation for Akt and MAPK expression among primary tumours and related metastases." (PMID 17579627, 2007). "Additionally, we found that the RNF43 G659Vfs*41 mutant, a hotspot frameshift mutation in human colorectal tumors that may not potentiate WNT signaling, elevates EGFR protein levels, suggesting that this mutation may exert its oncogenic role in cancer through EGFR upregulation." (PMID 38260423, 2024).
esophageal squamous cell carcinoma (126 papers, 2010 to 2026). Esophageal squamous cell carcinoma (ESCC) is a type of esophageal carcinoma (EC) that can affect any part of the esophagus, but is usually located in the upper or middle third. "CALM1 encodes a calcium-binding protein that is associated with esophageal squamous cell carcinoma and resistance to EGFR-antagonistic muscle." (PMID 39590360, 2024). "Consistently, EGFR overexpression and amplification were often seen in esophageal squamous cell carcinoma (ESCC) and associated with advanced stage and shorter survival." (PMID 36812484, 2023). "Epidermal growth factor receptor pathway genes significantly associated with risk of esophageal squamous cell carcinoma*." (PMID 23874846, 2013). "The aim of this study was to investigate the existence of EGFR mutations in Chinese esophageal squamous cell carcinomas." (PMID 24103528, 2013). "Furthermore, we observed that high PPAR activity correlated with mutations in the PCLO gene, which encodes a protein involved in synaptic function and has been linked to oncogenic signaling in cancer like EGFR signaling in esophageal squamous cell carcinoma." (PMID 39735727, 2024). "The epidermal growth factor receptor (EGFR) is widely overexpressed in esophageal squamous cell carcinoma (ESCC) and it results is associated with a poor prognosis." (PMID 26124180, 2015). "EGFR is highly expressed in esophageal squamous cell carcinomas (ESCCs), highlighting its potential as a therapeutic target." (PMID 40722671, 2025). "Elevated EGFR expression and increased EGFR copy number were prevalent in esophageal squamous cell carcinoma and contributed to malignant biological behaviors." (PMID 41227364, 2025). "Their mechanistic studies showed a significant downregulation of EGFR signaling in an in vitro model of esophagus squamous cell carcinoma (ESCC)." (PMID 39125273, 2024). "Previous studies have shown that many EGFR TKIs, including erlotinib, gefitinib, cetuximab and icotinib are effective and safe for patients with esophageal squamous cell carcinoma (ESCC)." (PMID 37251922, 2023). "Overexpression of EGFR in esophageal squamous cell carcinoma (ESCC) patients varies between 33.3 and 72.1%." (PMID 36090901, 2022). "In esophageal squamous cell carcinoma, PD-L1 expression can also be increased by chemotherapeutic treatments through activating the EGFR/ERK signaling pathway." (PMID 34805266, 2021). "Hyperactivation of the EGFR/MAPK signaling often leads to various cancers such as esophageal squamous cell carcinoma and CRC58,59." (PMID 31853225, 2019). "Epidermal growth factor receptor (EGFR) is overexpressed and considered as a proper molecular target for diagnosis and targeted therapy of esophageal squamous cell carcinoma (ESCC)." (PMID 30373221, 2018). "About 50–70% of patients with esophageal squamous cell carcinoma were accompanied by high expression levels of the epidermal growth factor receptor (EGFR)." (PMID 30477458, 2018). "We have identified NFkB as a central regulator of invasion in esophageal squamous cell carcinoma when p120ctn is down-regulated and EGFR is overexpressed." (PMID 29541406, 2018). "A previous study showed that PPAR-γ partial agonists induce cell cycle arrest by reducing the levels of p-EGFR, Akt, and p21 in esophageal squamous cell carcinoma." (PMID 28052030, 2017). "EGFR has also been reported to be over-expressed in esophageal squamous cell carcinoma (ESCC), a kind of cancer arising from the esophagus – the food pipe that runs between the throat and the stomach." (PMID 29019267, 2017). "Epidermal growth factor receptor (EGFR) plays a pivotal role in the pathophysiology of esophageal squamous cell carcinoma (ESCC)." (PMID 28764725, 2017).
esophageal squamous cell carcinoma (continued). "We established a cellular model system composed of two cell lines representing HER2 overexpressing esophageal adenocarcinomas (EACs) and EGFR overexpressing esophageal squamous cell carcinomas (ESCCs)." (PMID 28128281, 2017). "In our recent study, we made diagnostic and therapeutic convergence radiopharmaceutical, 64Cu-/177Lu-cetuximab for imaging and therapy in EGFR expressing esophageal squamous cell carcinoma (ESCC) model." (PMID 29190900, 2017). "Because EGFR is highly expressed in the majority of esophageal squamous cell carcinomas (ESCCs), we investigated the efficacy of Sym004 in human ESCC cell lines." (PMID 28038457, 2017). "This study aimed to search for a molecular marker for targeted epithelial growth factor receptor (EGFR) inhibitor Icotinib by analyzing protein expression and amplification of EGFR proto-oncogene in esophageal squamous cell carcinoma (ESCC) patients." (PMID 27013591, 2016). "And esophageal squamous cell carcinomas (ESCCs) predominantly show alterations of EGFR, whereas esophageal (Barrett’s) adenocarcinomas (EACs) frequently show HER2 gene amplification and protein overexpression." (PMID 25953424, 2015). "Nimotuzumab also promoted radiosensitivity of esophageal squamous cell carcinoma cells by up-regulating IGFBP-3 through EGFR-dependent pathway." (PMID 25918252, 2015). "The present study showed that ADAM17 expression had a positive correlation with EGFR expression indicating that in patients with esophageal squamous cell carcinoma, certain target EGFR drugs produce tolerance." (PMID 25351873, 2015). "The aim of the current study was to investigate the prognostic significance of epidermal growth factor receptor (EGFR) in patients with locally advanced esophageal squamous cell carcinoma (ESCC) receiving concurrent chemoradiotherapy (CCRT)." (PMID 24944678, 2014). "Although epidermal growth factor receptor (EGFR) inhibitor treatment showed modest response in several clinical trials in esophageal squamous cell carcinoma (ESCC) patients, it has been reported that the frequency of EGFR mutations varied largely." (PMID 24103528, 2013). "Epidermal growth factor receptor (EGFR) signaling is one of the most promising targets for molecular-targeted therapies in esophageal squamous cell carcinoma (ESCC)." (PMID 23274581, 2013). "A prospective clinical trial on concurrent use of chemoradiation and nimotuzumab, a monoclonal antibody against epidermal growth factor receptor, is underway in our center in an effort to further improve local control and survival for esophageal SCC patients." (PMID 22913676, 2012). "Esophageal squamous cell carcinoma (ESCC) represents a major therapeutic challenge due to the rapid development of resistance to epidermal growth factor receptor-tyrosine kinase inhibitors (EGFR-TKIs)." (PMID 41754923, 2026). "Therefore, the effects of ADAM9 KD on EGFR activation observed previously are likely specific to the esophageal squamous cell carcinoma cells examined, and there are alternative mechanisms through which ADAM9 regulates Akt in other cells and tissues." (PMID 35780836, 2022). "For EGF, a study showed that PD-L1 expression increased in an EGFR-dependent manner when EGFR signalling was activated and decreased when EGFR signalling was blocked in esophageal squamous cell carcinoma, and this was through EGFR-PI3K-AKT, EGFR-Ras-Raf-Erk, and EGR-PLC-gamma signalling pathways." (PMID 30770752, 2019). "Lymph node metastasis, TNM stage, ADAM17 and EGFR protein expression may be used as independent prognostic indicators of esophageal squamous cell carcinoma (all P<0.05)." (PMID 25351873, 2015). "We explored whether expression and activation of EGFR and several components on its downstream pathways have prognostic significance in patients with esophageal squamous cell carcinoma (ESCC)." (PMID 26338103, 2015).